IL6 (interleukin 6)
Diseases named in the same sentence as IL6 in open-access papers (continued):
Sharing a sentence is not in itself a finding about the gene and the disease.
endometriosis (364 papers, 2005 to 2026). The growth of functional endometrial tissue in anatomic sites outside the uterine body. "These carotenoids can downregulate the expression of pro-inflammatory cytokines such as IL-6 and IL-1β, which are heavily implicated in the inflammatory milieu of endometriosis." (PMID 39968397, 2025). "In conclusion, our data demonstrates the diagnostic potential of IL-6 and suPar as pro-inflammatory serum biomarkers in endometriosis." (PMID 40542028, 2025). "Increased serum levels of TNF-α, IL-6, and IL-1β, released from disease-associated macrophages, were observed in patients with endometriosis-induced infertility, creating a feedforward loop to aggravate endothelial cell activation." (PMID 40130159, 2025). "By encouraging tumor cell survival, proliferation, angiogenesis, and the release of pro-inflammatory cytokines including IL-6, this pathway plays a significant mechanistic role in both endometriosis-associated ovarian and endometrial malignancies." (PMID 41465243, 2025). "For instance, a significant decrease in genes associated with endometriosis and inflammation, such as IL-6 and IL-8, was observed." (PMID 41170181, 2025). "High levels of IL-6 are detected in follicular fluid from naturally mature follicles in patients with moderate and severe endometriosis, which is associated with lower pregnancy rates." (PMID 40130159, 2025). "It was confirmed by another meta-analysis of 34 studies which included 7521 women that additionally found associations between some variants of IL-6 gene polymorphism and increased risk of the development of endometriosis in Asian and Chinese populations." (PMID 40507929, 2025). "Increased IL-6 is also closely associated with abnormal ovarian lipid metabolism and reduced oocyte quality in endometriosis patients, PCOS patients, and obese women." (PMID 39704538, 2025). "The anti-inflammatory effects of diets high in ω-3 PUFAs, which are achieved by reducing TNF-α and IL-6 levels, contribute to lowering the risk of endometriosis among women." (PMID 40313408, 2025). "Among the molecular changes implicated in endometriosis-associated follicular dysfunction, IL-6 and cortisol have drawn attention." (PMID 41463303, 2025). "Endometriosis-associated angiogenesis is driven, among others, by proangiogenic cytokines such as IL-1β, IL-6, IL-8, and IL-17A." (PMID 39859551, 2025). "The pathogenesis of endometriosis is generally associated with inflammatory processes, and in addition to NO, substances such as IL-1, IL-6, PGE2, COX-2, and SOD have been observed." (PMID 40227209, 2025). "These cells are then activated by the cytokines secreted by the macrophages, including TNFa, Il12, IL6, and Il1b, which cause their proinflammatory anti-endometriosis activation." (PMID 39253270, 2024). "Oestrogen is associated with the release of IL-6 from macrophages, one of the main pro-inflammatory cytokines present in the endometriosis microenvironment." (PMID 39596309, 2024). "IL-6 levels are elevated in the PF of patients with active red-colored endometriosis, indicating a correlation with endometriosis-associated infertility." (PMID 38612685, 2024). "IL-6 is a well-known inflammatory marker of LPS, and IL-6 has also been shown to be a useful diagnostic marker for endometriosis, which is a chronic inflammatory disease." (PMID 38396694, 2024). "Macrophages in endometriosis produce IL-6, which is implicated in monocyte recruitment and, together with its receptor (IL-6R), regulates endometrial stromal cell growth in vitro." (PMID 39458478, 2024). "Among the 41 cytokines examined, genetically predicted platelet-derived growth factor-BB (PDGF-bb) and IL-6 showed a significant association with the risk of endometriosis in at least 1 MR method." (PMID 39029049, 2024). "Conversely, elevated levels of IL-6 were linked to a heightened risk of endometriosis, yielding an OR of 1.351 (95% CI: 1.015–1.797, P = .039)." (PMID 39029049, 2024).
endometriosis (continued). "These cellular processes are implicated in the early development of endometriotic lesions in vivo and in the overall development of endometriosis, further regulating genes associated with inflammation, including IL-6 and other pro-inflammatory cytokines." (PMID 38612685, 2024). "IL-6 expression was increased in the spontaneous baboon lesions and ES and is associated with chronic inflammation, endometriosis, and the presence of macrophages." (PMID 37104033, 2023). "Proinflammatory cytokines interleukin (IL)-1 and IL-6 have been shown to increase in endometriosis, and are known to be associated with myometrial contractility in active labor and preterm birth." (PMID 37629431, 2023). "On the other hand, IL-6 and IL-8 were overexpressed in PF of women suffering from endometriosis, which underlines the local pro-inflammatory environment seen in our patient collective." (PMID 36902452, 2023). "Interleukin (IL)-6, produced by endometriotic stromal cells in the presence of (IL)-1β, also increases angiogenic factors in neutrophils to stimulate endometriosis-associated angiogenesis." (PMID 35449709, 2022). "The peritoneal fluid and serum of patients with endometriosis and adenomyosis were found to have elevated levels of inflammatory cytokines, including IL-6, IL-8, IL-1b, IFN-γ, and TNF-α, which was associated with natural killer (NK) cell dysfunction." (PMID 35022045, 2022). "It should be underlined that in this study significantly higher serum IL-6 concentrations were found at stage IV of endometriosis in comparison to stage III." (PMID 33669013, 2021). "Endometriosis was also associated with elevated concentrations of IL-6, IL-10, and TGF-β1/2 as well as CCL20, CXCL8, CXCL9, and CXCL10." (PMID 34501240, 2021). "Specifically, elevated IL8 and MCP1 have been shown in the peritoneal fluid of women with endometriosis, and IL6, in the peritoneal fluid, has been linked to infertility in women with endometriosis." (PMID 33233463, 2020). "We additionally investigated the potential for these circulating miRNAs associated with endometriosis to alter adipocyte function by investigating their effect on the expression of IL-6 and HSL, important mediators of fat metabolism." (PMID 30982470, 2019). "Interleukin-6 (IL-6) is a cytokine and inflammatory marker implicated in the pathogenesis of endometriosis." (PMID 28694989, 2018). "The purpose of this study was to investigate the role of serum miR-17, IL-4, and IL-6 as early diagnostic markers of endometriosis." (PMID 29901577, 2018). "Accordingly, we aim to investigate the role of serum miR-17, IL-4, and IL-6 as early diagnostic markers of endometriosis." (PMID 29901577, 2018). "Among others, IL-6 and IL-8 have been studied extensively and implicated in the pathogenesis of endometriosis." (PMID 26898650, 2016). "Increased concentrations of IL‐6 are linked to proliferative disorders of the endometrium, such as endometriosis." (PMID 26471943, 2015). "Endometriosis and pelvic inflammation, diseases that manifest elevated levels of IL-6, are commonly associated with higher infertility." (PMID 22536401, 2012). "However, there are also studies that found associations between IL-6 levels in peritoneal fluid and stage of endometriosis." (PMID 40507929, 2025). "For instance, measuring the number of imDC or even the cytokines produced by the DC, like IL-1β, IL-6, and IL-10, in the peritoneal fluid of patients with endometriosis might serve as a diagnostic tool." (PMID 40747182, 2025). "At the molecular level, endometriosis is linked to a persistently inflammatory microenvironment that is marked by aberrant expression of estrogen and progesterone receptors, as well as high levels of proinflammatory cytokines such as prostaglandins and IL-6." (PMID 41465243, 2025).
endometriosis (continued). "PGE2, COX-2, IL-6, and IL 1-b activation resulted in higher levels of progesterone and cytokines in the peritoneal fluid, greater myometrial activity, and twice the risk of preterm birth in endometriosis-affected women as compared to the control group." (PMID 38276248, 2024). "IL6 gene polymorphisms have been extensively studied in relation to endometriosis." (PMID 39767772, 2024). "In endometriosis, the IL-6 pathway has long been implicated as a central driver of fibrotic pathology, with more recent studies identifying persistent activation of STAT3 via IL-6 trans-signaling as a driving mechanism, and highlighting IL-6 inhibition as a potential therapeutic intervention." (PMID 38689325, 2024). "Additionally, in endometriosis-associated ovarian carcinoma, increased of levels of IL-6 have been attributed to the NF-κB-IL-6-STAT3 signaling cascade." (PMID 39516433, 2024). "Moreover, recent studies have unveiled a noteworthy association between IL-6 and E2 in the advancement of endometriosis." (PMID 38384812, 2024). "In addition, the pro-inflammatory cytokines TNF-α and interleukin-6 (IL-6) also contain polymorphisms that have been linked to endometriosis." (PMID 37676242, 2023). "This may be related to the main pathogenesis of endometriosis causing a chronic inflammatory environment with increased levels of proinflammatory cytokines such as IL-1β, IL-6, and tumor necrosis factor-α." (PMID 37629431, 2023). "The −1031T/C polymorphism in the TNF-α gene reduces the risk of endometriosis, while −238A/G and −174C/G gene polymorphisms in the TNF-α and IL-6, respectively, may increase the risk of endometriosis in Asians." (PMID 37676242, 2023). "The diagnostic accuracy of serum IL-6 was recently tested for endometriosis prediction." (PMID 33669013, 2021). "Interestingly, ghrelin levels were not correlated with inflammatory cytokines classically associated with endometriosis, such as interleukin (IL-1β) 1β, IL-6, and tumor necrosis factor (TNF)." (PMID 33986637, 2021). "This complex activates IL-6 and IL-8 in endometriosis while its inhibition could be associated with the reduction of endometriosis development." (PMID 32244563, 2020). "In short, the present study characterizes the role of miR-17, IL-4, and IL-6 in the pathogenesis of endometriosis, suggesting the feasibility of using miR-17 and selected cytokines as a noninvasive diagnostic test for the detection of endometriosis." (PMID 29901577, 2018). "The abnormal presence of intrafollicular IL-1β and IL-6 could affect the follicular biology of endometriosis patients because low intrafollicular IL-6 is associated with a higher pregnancy rate." (PMID 30104541, 2018). "In human patients, the existence of endometriosis was found to be associated with increased levels of IL-6 in circulation and in the follicular fluid, and is proposed to be related to the impaired follicular development and decreased oestradiol production, which results in infertility." (PMID 23781169, 2013). "On the basis of the presence and activity of selected cytokines typical for various types of cellular response, it was indicated that the development of endometriosis is favored by Th2 cellular response and the associated cytokines, IL-4, IL-5, IL-6, IL-10 among others." (PMID 24298555, 2013). "In conclusion, elevated levels of IL-6 associated with endometriosis and pelvic inflammation may reduce the fertilizing capacity of human oocyte through a mechanism that involves impairment of the microtubule and chromosomal structure." (PMID 22536401, 2012). "MicroRNA alterations associated with endometriosis affect genes such as Cebpa, Cebpb, and Ppar-γ, which are involved in brown adipocyte differentiation, leptin and adipoq, which are involved in glucose metabolism, and IL-6 and HSL, which are involved in fat metabolism." (PMID 30982470, 2019).
endometriosis (continued). "For example, natural killer (NK) cells found in the peritoneal fluid of women with endometriosis show reduced cytotoxic activity, partly due to high levels of IL-6, which suppress important killing mechanisms like perforin and granzyme B." (PMID 41590512, 2026). "Increased concentrations of IL-6 have been detected in the serum and peritoneal fluid of women with endometriosis, suggesting its involvement in the inflammatory milieu of the disease." (PMID 41009445, 2025). "A study conducted on women with endometriosis found elevated levels of the inflammatory proteins interleukin IL‐6, IL‐8, and TNF‐α in their peritoneal fluid, indicating their potential contribution to the inflammatory processes associated with the condition." (PMID 39803270, 2025). "This study’s results indicated a correlation between elevated blood and peritoneal fluid IL-6 levels and the incidence of endometriosis-related infertility." (PMID 40938862, 2025). "Increased concentrations of IL-6 in the peritoneal fluid of patients with endometriosis underscore its role in disease progression." (PMID 40938862, 2025). "Endometriosis is characterised by elevated levels of pro-inflammatory factors such as interleukin 6 and 8 (IL-6/IL-8), tumour necrosis factor alpha (TNF-α), and prostaglandin E2 (PGE2)." (PMID 41303437, 2025). "In our study, only IL-6 showed significant elevation in the serum of endometriosis patients independently of disease severity, menstrual cycle, or medication and did not change in the tissue." (PMID 40724945, 2025). "Evidence suggests that the eutopic endometrium of women with endometriosis also exhibits inflammatory changes, such as increased macrophage numbers and elevated basal IL-6 production." (PMID 41145947, 2025). "Recent studies show that sustained STAT3 activation promotes endometriosis fibrosis by enhancing IL-10 and IL-6 anti-inflammatory effects." (PMID 41170181, 2025). "This suggests that the dysregulated expression of VEGF, TNF‐α, and IL‐6 contributes to the abnormal angiogenic processes observed in endometriosis." (PMID 39803270, 2025). "BEVs can be formed from the microbiota in the endometrial fluid and can induce the secretion of TNF, IL-6, and IL-17, which are involved in endometriosis." (PMID 40508002, 2025). "Immunological Impact: Research on animals demonstrates that antibiotic treatment lowers levels of important inflammatory cytokines, including IL-1β, IL-6, and TNF-α, which are associated with endometriosis development." (PMID 40725782, 2025). "Studies have shown that patients with endometriosis develop high levels of IL-1β, IL-8, IL-6, and other pro-inflammatory factors." (PMID 40761347, 2025). "In eutopic endometrial stromal cells of patients with endometriosis, in vitro treatment inhibits the secretion of IL-6, IL-8, G-CSF, MCP-1, and RANTES." (PMID 40508002, 2025). "Regarding inflammation, downregulation of miR-10b-5p as in our study, resulted in increased IL-6 secretion, promoting inflammation in endometriosis." (PMID 41013698, 2025). "Increased levels of IL-6 were found in women with stage I-II endometriosis, with 75% sensitivity and 83.3% specificity." (PMID 40507929, 2025). "The specific profile of inflammatory mediators dominant in endometriosis (high IL-1β, IL-6, IL-8, TNF-α, CCL2/MCP-1, MMPs) shows a striking resemblance to the canonical components of the SASP secreted by senescent cells." (PMID 41145947, 2025). "IL-6 was significantly higher in the stage I–IV endometriosis group than that in healthy controls, but its concentration was not affected by disease severity, menstrual cycle phase, or medication status." (PMID 40724945, 2025). "MCs release pro-inflammatory cytokines like TNF-α and IL-6, which contribute to the inflammatory environment in endometriosis, leading to the progression of the disease and pain." (PMID 40747182, 2025).
endometriosis (continued). "Patients with endometriosis show elevated concentrations in peritoneal fluid of key cytokines supporting cell-mediated immunity and inflammation: IL-1β, IL-6, and TNF-α." (PMID 41488658, 2025). "Treatment for endometriosis must involve interventions that can modulate the multidimensional nature of the disease, which involves inflammatory (IL-6, TNF-α, CCL2), hormonal (ERβ, aromatase, 17β-estradiol) and oxidative (MDA, ROS, SOD/GPx) factors." (PMID 41303437, 2025). "For example, increased levels of the cytokine interleukin-6 (IL-6) have been reported in the serum of patients with endometriosis, leading to persistent activation of the signal transducer and activator of transcription 3 (STAT3) protein." (PMID 40422245, 2025). "Women with endometriosis have elevated levels of key pro-inflammatory cytokines, i.e., IL-1β, IL-6, and TNF-α." (PMID 39859551, 2025). "In endometriosis, IL-6 drives a pro-inflammatory microenvironment that promotes lesion survival and impairs endometrial receptivity." (PMID 41227338, 2025). "OCCC is frequently linked to endometriosis and characterized by mutations in ARID1A and PIK3CA, hyperactivation of the PI3K/Akt/mTOR pathway, and overexpression of VEGF, HIF-1α, and IL-6." (PMID 41383608, 2025). "Prior studies have shown that peritoneal fluid from endometriosis patients contains elevated levels of pro‐inflammatory cytokines, such as IL‐6, IL‐8, and TNF‐α, as well as increased oxidative stress markers." (PMID 40922382, 2025). "Our observation of a sustained increase in Il6 mRNA in ADM uteri at both 1- and 3-month post-adenomyosis induction aligns with clinical reports of elevated IL-6 in the peritoneal fluid and lesional endometrium of patients with adenomyosis and endometriosis." (PMID 41298316, 2025). "By encouraging inflammatory reactions and cell proliferation, IL-6 primarily worsens the disease course of endometriosis." (PMID 39822256, 2025). "In the context of endometriosis, C5a stimulates peritoneal macrophages to produce pro-inflammatory cytokines IL-1β, IL-6, TNF-α, and IL-8, enhancing the cytokine imbalance characteristic of this disease (Section 4)." (PMID 41488658, 2025). "In summary, this study has systematically investigated the expression profiles of PGC-1α, ERRα, ERβ, IL-6, caspase-3, and caspase-9 in endometriosis tissues and their effects on endometrial stromal cells." (PMID 39822256, 2025). "IL-6 is reported as an important cytokine in both the endometrium and endometriosis lesions in women with endometriosis and is known to be both proinflammatory and antiinflammatory." (PMID 39836475, 2025). "Silymarin has been shown to significantly reduce interleukin-6 levels, the size of endometrioma lesions, and pain symptoms in women with endometriosis, according to a randomized, double-blind, placebo-controlled trial." (PMID 40725782, 2025). "Another glycoprotein glycodelin A levels in serum and peritoneal fluid has a 91.7% sensitivity and 75% specificity for endometriosis, while IL-6 levels have 93.8% and 80%, respectively, and intercellular adhesion molecule 1 has 58.3% and 60.0%, respectively." (PMID 40507929, 2025). "NLRC5 levels are higher in the ectopic and eutopic endometria of endometriosis patients compared to those with leiomyoma, peaking in the ectopic endometrium, and it suppresses IL-6 and TNF-α." (PMID 40508002, 2025). "This lack of responsiveness is further amplified by the chronic inflammatory state typical of endometriosis where cytokines such as IL-6 and TNF-α can work in tandem to elevate VEGF levels." (PMID 39982662, 2025). "IL-6 is a pro-inflammatory cytokine that has been found to be elevated in the serum and peritoneal fluid of women with endometriosis, suggesting a potential role in the disease’s pathology." (PMID 40724945, 2025). "MIF and IL-6 were higher in stage I–IV endometriosis, with MIF also higher in the secretory phase and in patients not receiving oral contraceptives." (PMID 40724945, 2025).